CCL5 (C-C motif chemokine ligand 5)
Diseases named in the same sentence as CCL5 in open-access papers (continued):
Sharing a sentence is not in itself a finding about the gene and the disease.
ovarian carcinoma (continued). "In this model, the upregulation of CCL2 and CCL5 could explain the increase in TILs, as CCL2 can induce TILs in ovarian cancer." (PMID 30487462, 2018). "CD133+ ovarian cancer stem cells cultured on a cell culture matrix formed fluid-conducting tube networks activated NF-κB and STAT3 signal pathways, through autocrine chemokine (C-C motif) ligand 5 (CCL5) upregulation promoting differentiation into endothelial cells." (PMID 31861720, 2019). "Therefore, our present study together with previous findings suggest that CD133+ ovarian cancer cells are distinct from the CD133− population in terms of metastatic capability and CCL5 production, but the former can enhance the metastatic capacity of the latter." (PMID 25788271, 2015). "Finally, as with murine ovarian cancer cells, knocking down individual dsRNA PRRs did not completely abolish the induction of RANTES/CCL5 at the level of RNA or protein upon stimulation with dsRNA, suggesting a contribution of several receptors to the inflammatory response studied here." (PMID 30613350, 2018). "Interestingly, although the combination of TNFα and IFNγ could induce the production of CCL5 in ovarian cancer ascites cells or macrophages, their joint blockade did not abrogate induction of CCL5 in co-cultures of activated CD8+ T cells with ascites cells or myeloid cells." (PMID 41142824, 2025). "Using female healthy donors with no history of ovarian cancer, we were also able to detect levels of CCL2, CCL4, CCL5, CXCL10 and CXCL12." (PMID 41424784, 2025). "CCR5 antagonist anibamine and its analogues inhibited the CCL5-induced proliferation and the intracellular Ca2+ flux of OVCAR-3 ovarian cancer cells, with no significant toxicity in NIH/3T3 fibroblasts." (PMID 32630699, 2020). "Indeed, we found contact-dependent secretion by hMSCs of CCL10 (IP-10), CCL5 (RANTES), HGF, and GM-CSF in third party co-cultures with ovarian cancer cell lines and hMSCs (data not shown)." (PMID 20436665, 2010).
glioma (69 papers, 2012 to 2025). A benign or malignant brain and spinal cord tumor that arises from glial cells (astrocytes, oligodendrocytes, ependymal cells). "The inflammatory mediator chemokine C─C ligand 5 (CCL5) has been implicated in tumor growth and migration across various cancer types, including glioma." (PMID 40620486, 2025). "For instance, midkine, released by retinal ganglion cells, stimulates CD8+ lymphocytes to secrete the chemokine CCL4, which subsequently activates glioma-associated microglia or macrophages to secrete CCL5." (PMID 40092993, 2025). "Interruption of this cellular circuit using glutamate receptor, IL-1β or Ccl5 inhibitors abrogates injury-induced glioma progression, thus establishing a causative relationship between injury and tumorigenesis." (PMID 38308315, 2024). "CCL5 (derived from glioma-associated microglia/brain macrophages [GAMs]) enhances glioma cell invasiveness through a novel calcium-dependent MMP2 signaling pathway." (PMID 39124881, 2024). "On other hand, CCL5 as an inflammatory mediator also seems to be implicated in the glioma-related developmental process as revealed by the in vitro study of Yu-Ju Wu and colleagues." (PMID 36980182, 2023). "chemokine (C-C motif) ligand 5 (CCL5) was reported to modulate the migratory and invasive activities of human glioma cells in association with MMP2 expression." (PMID 35600367, 2022). "In GMB, CCL5 (derived from glioma-associated microglia/brain macrophages [GAMs]) enhances glioma cell invasiveness through a novel calcium-dependent MMP2 signaling pathway." (PMID 36591235, 2022). "Higher expression of CCL5 protein has also been detected in glioma tissues and is associated with glioma‐associated microglial activation." (PMID 33960680, 2021). "As observed, COX-2 (Ptgs2), IL-1β, and CCL5 are among the 25 highest upregulated genes in glioma-associated microglia/macrophages." (PMID 29258556, 2017). "We demonstrated an association between increases of glioma CCL5 and CCR5+CD38+HLA-DR+CD8+ TILs." (PMID 31649684, 2019). "CCL5 is synthesized and secreted by glioma-associated microglia, and thus a CCL5-mediated activation of NF-κB in GSCs may contribute to EC trans-differentiation in GBM, as is the case in other cells." (PMID 28598356, 2017). "The emergence of such autoregulatory chemokine/chemokine receptor loops relevant to glioma growth prompted us to examine a recently-identified paracrine signal (CCL5), produced by low-grade glioma-associated microglia, as a potential autocrine signaling molecule in high-grade glioma." (PMID 28380429, 2017). "This concept presents a novel approach for the treatment of gliomas and other cancers in which CCL5 and related signaling pathways play a role in tumor progression." (PMID 40620486, 2025). "The findings from these studies suggest that CCL5 modulates the migratory and invasive capabilities of human glioma cells in conjunction with MMP2 expression." (PMID 40620486, 2025). "Overall, these findings suggest that the modulation of glioma CaMKII is a potential therapeutic target for reducing glioma growth by limiting the effects of CCL5 on glioma invasion." (PMID 40620486, 2025). "In response to CCL5, glioma cells show a synchronized increase in intracellular calcium levels and p‐CaMKII and p‐Akt expression." (PMID 40620486, 2025). "In this manner, Nf1-mutant neurons initiate a paracrine stromal cascade in which midkine induces CD8+ T cells to produce Ccl4, which in turn stimulates TAM expression of Ccl5, a cytokine that increases glioma growth." (PMID 41497446, 2025). "In the glioma microenvironment, microglia can be recruited by gliomas through chemoattractants such as CCL5, CCL2, CX3CL1, and CXCL12, and can penetrate the tumor." (PMID 38549161, 2024). "Chemokines associated with T cell trafficking (CCL3, CCL5, CXCL9, and CXCL10) were all upregulated in KR158B glioma tissue compared to naïve tissue." (PMID 39272914, 2024).
glioma (continued). "Jointly with matrix metalloproteinase-2 (MMP2), CCL5 regulates the migratory and invasive flow of glioma cells and consequently increases intracellular calcium levels as well as p-calcium/calmodulin-dependent protein kinase II (p-CaMKII) and p-AKT expressions." (PMID 36980182, 2023). "Our study showed that CCL5 induced by intrinsic LAIR1 expression in glioma cells plays an important role in microglia/macrophage polarization, although more research is needed to determine the relationship in other cell types." (PMID 37845206, 2023). "Specifically, LAIR1 partially contributes to the immunosuppressive glioma microenvironment by CCL5-mediated microglia/macrophage polarization." (PMID 37845206, 2023). "A previous study revealed elevated mRNA and protein expression of CCL5 in tumor tissue samples collected from patients with high-grade glioma." (PMID 37627528, 2023). "In vitro, CCLs such as CCL2 and CCL5 exhibited a meaningful effect on the attraction and migration of glial tumor cells." (PMID 36980182, 2023). "LAIR1 specifically supports in the immunosuppressive glioma microenvironment via CCL5-mediated microglia/macrophage polarization." (PMID 37845206, 2023). "Under the stimulation of CCL5, glioma cells subsequently increase intracellular calcium levels, phosphorylated Ca2+/calmodulin-dependent protein kinase II (p-CaMKII), and p-Akt expression levels." (PMID 37012233, 2023). "CCL5 is associated with the upregulation of MMP2, thus contributing to the invasion and migration of glioma." (PMID 37012233, 2023). "In response to CCL5, glioma cells synchronously upregulated intracellular calcium levels and p-CaMKII and p-Akt expression levels." (PMID 35600367, 2022). "Glioma cells that have been stimulated with CCL5 show increased intracellular calcium levels and elevated Akt (p-Akt) and Ca2+/calmodulin-dependent protein kinase II phosphorylation (p-CaMKII) in a time- and dose-dependent manner." (PMID 36555253, 2022). "Glioma cells tended to migrate toward GAM-conditioned media activated by the granulocyte-macrophage colony-stimulating factor (GM-CSF) in which CCL5 was abundant." (PMID 35600367, 2022). "Low-grade gliomas highly express CCL2-4, high-grade gliomas express CCL5, while diffuse midline gliomas have basal expression of all chemokines." (PMID 35464481, 2022). "On the flip side, small interfering RNA silencing of CaMKII resulted in inhibition of CCL5-mediated glioma invasion." (PMID 36555253, 2022). "Previous studies have shown that CCL5 played an indispensable role in the formation of glioma cells." (PMID 36159780, 2022). "In response to CCL5, glioma cells undergo a synchronized increase in intracellular calcium levels and glioma cells tend to migrate toward GAM-conditioned media activated by a granulocyte-macrophage colony-stimulating factor (GM-CSF) in which CCL5 is abundant." (PMID 35741603, 2022). "CCL5 in macrophage-conditioned media enhanced GBM cell invasion under hypoxic conditions, and CCL5 was critical for Neurofibromatosis-1 glioma growth in response to tumor-associated microglia." (PMID 33923334, 2021). "The fact that C-C motif chemokine ligand 5 (CCL5) modulates invasive and migratory behaviors of glioma through the phosphorylation of calmodulin-dependent protein kinase II (CaMKII) renders CCL5 and CaMKII interesting targets to halt glioma progression." (PMID 34671362, 2021). "As such, Ccl5 operates to increase low-grade and high-grade glioma survival through CD44 binding and downstream signaling." (PMID 32358581, 2020). "CCL2 expression pattern was very similar to that of CCRL2, and significantly increased with higher glioma tumor grade, whereas CCL5 expression exhibited an inverse relationship and its level decreased with increasing tumor grade." (PMID 32456359, 2020). "These authors showed that CCL5 established autocrine signaling in high-grade glioma by affecting growth regulatory circuit that was critical in particular for mesenchymal (MES) glioblastoma subtype." (PMID 32545571, 2020).
glioma (continued). "Taken together, these results establish Ccl4 as the cytokine responsible for inducing microglia Ccl5 production relevant to glioma growth regulation." (PMID 32358581, 2020). "Immunohistochemical staining of glioma samples from patients with GBM revealed that TILs were located in areas where CCL5 was abundantly expressed." (PMID 31649684, 2019). "In the present study, we also found an elevation of CCL5 in the glioma microenvironment, which is in accordance with the infiltration of CD38+HLA-DR+CD8+ TILs via CCR5 expression." (PMID 31649684, 2019). "Higher CCL5 protein and mRNA levels were identified in glioma tissues, which was consistent with the immunohistochemistry results revealing both CCL5 and CD38+HLA-DR+CD8+ T cell expression." (PMID 31649684, 2019). "Second, CCL5 mRNA and protein expression are elevated in both tumor tissue and serum from patients with high-grade glioma." (PMID 28380429, 2017). "Interestingly, it regulates IL6 and CCL5 expression in glioma cells, exacerbating the neuroinflammatory process." (PMID 39962586, 2025). "Furthermore, the CCL5‐induced invasion of glioma cells and the corresponding increase in MMP2 are suppressed when p‐CaMKII is inhibited." (PMID 40620486, 2025). "Future studies will further investigate the role of CCL5 in cell communication between T cell subsets or with other immune cells, conduct additional experiments, such as mechanism experiments and in vivo models, and consider other glioma types." (PMID 41155216, 2025). "HBS-101, a novel midkine inhibitor, reduced optic nerve proliferation, normalized RNFL thickness, and decreased the expression of tumor (Neu4, Gpr17) and TME (Ccl2, Ccl3, Ccl4, Ccl5) genes, supporting its continued development as a targeted therapy for pediatric NF1-associated glioma." (PMID 41497446, 2025). "Our investigation revealed a positive correlation between the expression of CLEC7A and monocyte chemoattractant factors (CCL2, CCL5) as well as factors implicated in M2 macrophage polarization (TGF-β1, CSF-1) in glioma samples obtained from both TCGA and CGGA databases." (PMID 38846954, 2024). "To evaluate the combined impact of the developing glioma and SorLA loss from host cells on the tumor microenvironment, we first assayed the levels of selected cytokines (TNFα, MIP2, CCL5, CXCL1, IL1β, IL2, IL6, and IL10) in the tissue lysates derived from tumor-bearing and tumor-free hemispheres." (PMID 38499808, 2024). "Previous studies from our laboratory have characterized a “neuron-immune-cancer cell” axis, in which neurons elaborate midkine in an activity-dependent manner, which stimulates T cell Ccl4 production to induce TAM (Tmem119+/Iba1+/CD45low/CD11b+ microglia) Ccl5-mediated support of glioma growth." (PMID 38308315, 2024). "Authors suggest that modulation of glioma calcium levels may restrict the effect of CCL5 on glioma invasion and could be a potential therapeutic target for alleviating glioma growth." (PMID 35741603, 2022). "The more of Th2 and the less of Th1 in the high risk score cluster indicated that the cellular immunity may be suppressed, and there may be more CCL5 to support the formation of gliomas." (PMID 36159780, 2022). "Caren’s work showed that immune cells could regulate glioma invasion and migration via CCL5, which was influenced by the levels of intracellular and extracellular calcium ions." (PMID 35646664, 2022). "Inhibition of p-CaMKII suppressed CCL5-mediated glioma invasion and upregulation of MMP2." (PMID 35600367, 2022). "What’s more, we verified that knockdown of PLK1 could increase the expression of the M1 macrophage chemokine CCL5 in glioma cell lines U87 and LN229." (PMID 36618405, 2022). "Additionally, microglia-derived CCL5 triggers upregulation of MMP2 in glioma cells through calcium and Akt signaling, which in response promotes ECM degradation and invasiveness in glioma." (PMID 34503065, 2021). "CCL5 neutralizing antibodies reduced glioma tumor growth in a murine model." (PMID 33923334, 2021).
glioma (continued). "Therefore, we first need to reveal the CCL5/CCR5 distribution in patients’ tissues with respect to glioma stage and glioblastoma subtype, and secondly CCL5 and CCR5 relative expressions in the isolated primary glioblastoma cell lines." (PMID 32545571, 2020). "Moreover, we demonstrate that NF1-mutant neurons support glioma growth by producing MDK, which activates T cells to produce Ccl4, a cytokine that induces microglia to express a critical glioma growth factor (Ccl5)." (PMID 32358581, 2020). "As in low-grade gliomas, for which we have shown low expression of both CCL5 and CCR5, we may speculate that the progression probably relays more on stromal cells’ supportive chemokine stimulation." (PMID 32545571, 2020). "We also explored the distribution of CCR5 and CCL5 among gliomas of different stages." (PMID 32545571, 2020). "The receptor repertoire involved in the CCL5-mediated control of glutamate exocytosis in human specimens could have been altered because of the pathological overexpression of CCL5 in glioma cells." (PMID 28928746, 2017). "Based on our previous studies examining CCL5 expression and function in low-grade glioma, we first sought to determine whether CCL5 expression was higher in human GBM tumors relative to non-neoplastic brain." (PMID 28380429, 2017). "However, the specific mechanisms through which CCL5 promotes glioma invasion remain largely unknown." (PMID 40620486, 2025). "Moreover, a more recent study has shown that expression of CD11a by microglia may play an important role in the production of glioma derived CCL5." (PMID 36555253, 2022). "Moreover, CCL5 is involved in tumour growth and cell migration in various cancers including glioma." (PMID 36555253, 2022). "The high-level expression of CCL5 may support immune escape and metastasis of glioma cells." (PMID 36159780, 2022). "However, it is unclear whether CCL5 in gliomas would also trigger similar Treg inhibition toward CD8+ TILs, as we only found a negligible population (<2%) of Treg characterized as Foxp3+ CD4+ (data not shown)." (PMID 31649684, 2019). "The cytokine-cytokine receptor pathway featured 35 genes (p = 3.79 × 10−7), such as CCL5, CXCL10, and IFNG, indicating impaired chemokine-mediated immune cell recruitment (e.g., CD8+ T cells and macrophages) in the immunosuppressive glioma microenvironment." (PMID 40406701, 2025). "In this study, we also showed that LAIR1 remarkably promoted the production of CCL5, TGFβ2, and IL33 in glioma cells, in a nuclear FAK-dependent manner." (PMID 37845206, 2023). "Especially, CCR5/CCL5 and CXCR6/CXCL16 signaling modulates TAM polarization, as well as the proliferation and invasion of glioma cells." (PMID 37818357, 2023). "These immune cells had the highest density in gliomas and possessed immunosuppressive cytokines and chemokines, including CXCL12, CXCL10, CCR5, CCR10, CCL5, and CCR2, to exert their immunosuppressive effects." (PMID 37515314, 2023). "Glioma-derived Granulocyte-macrophage colony-stimulating factor (GM-CSF) promotes activation of GAMs and production of CCL5, which further induce a series of calcium-dependent pathways such as p-PYK2 and p-CAMKII that lead to glioma progression." (PMID 35711434, 2022). "It has been also described that the CCL5/CCR5 axis increased cellular invasiveness via the induction of MMPs, and, more specifically, CCL5 modulated glioma cells’ migratory and invasive activities due to MMP2 upregulation." (PMID 36139013, 2022). "We confirmed that CCL5 and CCR5 proteins were overexpressed in glioma tissues (unpublished), and in a cohort of 65 patients, also mRNA levels were significantly higher compared with their normal counterparts." (PMID 33923334, 2021). "Preferential expression of CCL5 or CCR5 was identified in GBMs, IDH-wild-type gliomas and mesenchymal-like subtype gliomas." (PMID 34239070, 2021).